MTA1 (metastasis associated 1)
Diseases named in the same sentence as MTA1 in open-access papers (continued):
Sharing a sentence is not in itself a finding about the gene and the disease.
prostate carcinoma (50 papers, 2008 to 2025). A carcinoma that arises from epithelial cells of the prostate gland. "Metastasis-associated protein 1 (MTA1) is a dual coregulatory protein overexpressed in various cancers, including castration-resistant prostate cancer." (PMID 40023399, 2025). "Yet another pathway having major implications in advanced prostate cancer is metastasis-associated protein 1 (MTA1) signaling, which is strongly associated with clinically aggressive prostate cancer." (PMID 38611022, 2024). "The prostate-specific R26MTA1; Ptenf/f genetically engineered mouse model recapitulates features of PTEN-loss advanced prostate cancer facilitated by the overexpression of MTA1." (PMID 38611022, 2024). "We have previously reported increased levels of MTA1 in Pten-deficient and Pten-loss mouse models of prostate cancer, which affected downstream inflammation and cell survival pathways." (PMID 38611022, 2024). "In our previous studies of MTA1-associated prostate cancer progression, we found an inverse relationship between MTA1 overexpression and PTEN activation, which resulted in an aberrant activation of the AKT signaling pathway." (PMID 38611022, 2024). "We conclude that R26MTA1; Ptenf/f mice recapitulate key features of MTA1/mTOR signaling pathway activation-associated advanced prostate cancer and represent a useful model for exploring novel therapeutic approaches to manage advanced disease." (PMID 38611022, 2024). "In prostate cancer, metastasis associated protein 1 (MTA1) signaling is aberrantly activated due to overexpression of MTA1 and activation of associated pathways." (PMID 36091792, 2022). "Increased expression of MTA1 is associated with high Gleason score, recurrence, and metastasis in prostate cancer." (PMID 36091792, 2022). "In our previous studies, we have shown that stilbenes, such as resveratrol and pterostilbene, can act through metastasis-associated protein 1 (MTA1)-mediated mechanisms to prevent the progression of premalignant prostate cancer to adenocarcinoma." (PMID 36551523, 2022). "Another valuable MTA1-associated miRNA/target axis was identified from miRNA profiling studies and was functionally validated in prostate cancer: the miR-22/E-cadherin axis." (PMID 36091792, 2022). "Particularly, our group systematically reported on the chemopreventive and therapeutic roles of metastasis-associated protein 1 (MTA1)-mediated anticancer effects of Res, pterostilbene (Pter), and other stilbenes against prostate cancer." (PMID 33255879, 2020). "Multiple studies have indicated that the administration of PTER induces chemopreventive effects by targeting metastatsis-associated protein 1 (MTA1) in human prostate cancer." (PMID 32962067, 2020). "Among the MTA1-associated genes previously identified by our group from MTA1-ChIP analysis were Cyclin D1 and Notch 2, which were shown to be responsive to Pter treatment and directly regulated by MTA1 in prostate cancer cell lines." (PMID 33255879, 2020). "Pterostilbene is a dietary analog of resveratrol, having metastasis-associated protein 1 (MTA1)-targeted chemopreventive and therapeutic efficacy upon prostate cancer cells." (PMID 31597327, 2019). "The overexpression of metastasis-associated protein 1 (MTA1) in prostate cancer (PCa) contributes to tumor aggressiveness and metastasis." (PMID 31487842, 2019). "Overexpression of the epigenetic modifier metastasis-associated protein 1 (MTA1) is associated with aggressive human prostate cancer." (PMID 26943043, 2016). "Increased nuclear expression of MTA1 is associated with high Gleason score, aggressive disease, recurrence, and bone metastasis in human prostate cancer." (PMID 26943043, 2016). "To gain insights into the mechanistic basis for the MTA1 upregulation in Pten loss-driven prostate tumorigenesis and tumor progression, we studied the effects of MTA1 knockdown in the human prostate cancer cell lines, LNCaP and DU145." (PMID 26943043, 2016).
prostate carcinoma (continued). "Here, we show that high levels of MTA1 expression in Pten-loss prostate cooperate with key oncogenes, including c-Myc and Akt among others, to promote prostate cancer progression." (PMID 26943043, 2016). "Loss-of-function studies using human prostate cancer cells indicated direct involvement of MTA1 in inducing inflammation and epithelial-to-mesenchymal transition." (PMID 26943043, 2016). "For example, out of all the tissue types analyzed including adjacent normal, PIN, and prostate cancer, high protein levels of YB-1 and MTA1 in PIN lesions were the most significantly associated with an increased risk for PSA recurrence." (PMID 25797255, 2015). "Next, we sought to determine if there was a correlation between YB-1 and MTA1 protein levels and clinical factors historically associated with prostate cancer progression." (PMID 25797255, 2015). "Metastasis-associated protein (MTA1) inhibits cathepsin B expression in prostate cancer." (PMID 32727598, 2020). "MTA1 has been associated with the invasiveness of human prostate cancer cells." (PMID 31281798, 2019). "Human cervical cancer HeLa and human prostate cancer DU-145 cell lines were used to test if IL-17 regulates metastasis associated 1 (MTA1) mRNA and protein expression using quantitative reverse transcription-polymerase chain reaction and Western blot analysis, respectively." (PMID 31281798, 2019). "First, YB-1 and MTA1 levels can be used to risk-stratify prostate cancer patients to distinguish those who may benefit from immediate adjuvant therapy such as radiation after surgery." (PMID 25797255, 2015). "As such, high protein levels of YB-1 and MTA1 in PIN may predispose patients to a more aggressive prostate cancer when it develops, thereby increasing the risk for PSA recurrence or the need for future therapy after a prostatectomy." (PMID 25797255, 2015). "Human metastasis-associated gene 1 (MTA1) is highly associated with the metastasis of prostate cancer; however, the molecular functions of MTA1 that facilitate metastasis remain unclear." (PMID 23227138, 2012). "Our findings demonstrate that a gnetin C-supplemented diet effectively blocks MTA1-promoted tumor progression activity in high-risk premalignant prostate cancer, which indicates its potential as a novel form of nutritional interception for prostate cancer chemoprevention." (PMID 36551523, 2022). "Importantly, we explored the possible novel mechanism of GPE through metastasis-associated protein 1 (MTA1) downregulation in prostate cancer, since our previous studies indicated resveratrol (Res)- and pterostilbene (Pter)-induced MTA1-mediated anticancer activities in prostate cancer." (PMID 30463302, 2018). "Interestingly, although independent from MTA1, pterostilbene also downregulated the AR levels, further strengthening its potential as a suitable chemopreventive agent to reduce the risk of prostate cancer." (PMID 26943043, 2016). "AR is the most critical transcription factor in prostate cancer, but other dysregulated pathways also exist, such as the MTA1/PTEN/AKT pathway." (PMID 40023399, 2025). "Gnetin C displayed substantial inhibitory effects in prostate cancer cells expressing MTA1, while in MTA1 knockdown cells, Gnetin C showed partial MTA1-independent mechanisms that inhibit cell metastatic potential and induce apoptosis." (PMID 40077738, 2025). "We report here that gnetin C effectively suppressed the MTA1/mTOR pathway indicated by the downregulated MTA1 and the associated reduced phosphorylation of AKT, mTOR, S6K, 4EBP1, and CyclinD1 in PC3M prostate cancer cells." (PMID 38611022, 2024).
prostate carcinoma (continued). "Targeted interception strategies by plant-based polyphenols, specifically stilbenes, have shown great promise against MTA1-mediated prostate cancer progression." (PMID 38611022, 2024). "Pterostilbene reduced MTA1-dependent cell survival and metastasis in prostate cancer by inhibiting MTA1 expression, disrupting the MTA1-histone deacetylase complex, and restoring PTEN expression." (PMID 38155902, 2023). "Gnetin C acts through MTA1/ETS2-mediated mechanisms in prostate cancer and shows significant MTA1-mediated inhibitory effects on cell viability, colony formation and migration, and induces cell cycle arrest and cell death at 25 and 50 μM concentrations." (PMID 37631147, 2023). "We have also demonstrated that MTA1 is a molecular target for stilbene polyphenols, such as resveratrol, pterostilbene, and gnetin C, in prostate cancer, in vitro and in vivo." (PMID 36551523, 2022). "MTA1 plays a critical role in different stages of prostate cancer, including chronic inflammation, tumor growth, epithelial-to-mesenchymal transition (EMT), invasion, migration, angiogenesis and metastasis." (PMID 36091792, 2022). "The results from our studies suggest that miR regulation is conserved among stilbene family members and that the identified MTA1-miRNA network regulated by stilbenes plays a significant role in prostate cancer progression." (PMID 36091792, 2022). "MTA1-promoted miR-22-regulation of this adhesion factor makes the MTA1/miR-22/E-cadherin axis critical for promoting tumor invasiveness in prostate cancer cells." (PMID 36091792, 2022). "In conclusion, our results established the MTA1/PTEN/p-Akt axis as a suitable target for gnetin C interception in early-stage prostate cancer in mice." (PMID 36551523, 2022). "Particularly, our recent report showed that a pterostilbene-supplemented diet fed to mice with early-stage prostate cancer can block the progression of prostate cancer through the inhibition of MTA1-mediated signaling." (PMID 36551523, 2022). "MTA1 is a chromatin modifier and transcriptional regulator, and plays a cancer-promoting role in all stages of prostate cancer." (PMID 36551523, 2022). "The aim of this review is to outline known stilbene-regulated miRNAs in cancer, with a special focus on the interplay between various miRNAs and MTA1 signaling in prostate cancer." (PMID 36091792, 2022). "Further analysis of prostate tissues and prostate cancer cell lines confirmed the potent MTA1 inhibitory potential of gnetin C compared to pterostilbene." (PMID 36551523, 2022). "We have also shown the MTA1-mediated and MTA1 independent chemopreventive and therapeutic value of Gnetin C in prostate cancer in vitro and in vivo." (PMID 36091792, 2022). "Downregulation of MTA1 by RVT triggers apoptosis in prostate cancer cells (PCa) by activating pro-apoptotic genes Bax and p21." (PMID 36233012, 2022). "PTEN, a tumor suppressor, is deleted on chromosome 10 in prostate cancer or inactivated by MTA1/HDAC inhibitors." (PMID 36233012, 2022). "MTA1 is an epigenetic reader and an oncogenic transcription factor that is overexpressed in advanced prostate cancer and metastasis." (PMID 36091792, 2022). "Our group has tested the MTA1-targeted chemopreventive and therapeutic potential of stilbenes and grape extracts in murine prostate cancer models." (PMID 36551523, 2022). "Studies have demonstrated the MTA1-mediated chemopreventive and therapeutic effects of natural stilbenes in prostate cancer." (PMID 36091792, 2022).
prostate carcinoma (continued). "A clinical trial evaluating the therapeutic efficacy of pterostilbene, an MTA1 inhibitor, for the treatment of prostate cancer has been designed and is ongoing [Levenson, A.S. (2018) MTA1-targeted strategies for prostate cancer management." (PMID 34502289, 2021). "We recently reported that Gnetin C, a resveratrol (Res) dimer, demonstrated more potent inhibition of metastasis-associated protein 1/v-ets avian erythroblastosis virus E26 oncogene homolog 2 (MTA1/ETS2) axis in prostate cancer cell lines than other stilbenes." (PMID 33255879, 2020). "Resveratrol can reverse the progression of prostate cancer by inhibiting MTA1 that binds to HDAC, forming the MTA1/HDAC complex." (PMID 32585896, 2020). "We demonstrated that Gnetin C inhibited MTA1-mediated cell viability, clonogenic survival, migration and induced MTA1-mediated apoptosis more potently than Res and Pter in prostate cancer cells specifically acting through MTA1/ETS2 pathway." (PMID 33255879, 2020). "For example, resveratrol (Compound 36) can decrease the expression of MTA1 in prostate cancer cells, which then reduces the amount of MTA1:HDAC1 complexes." (PMID 33266366, 2020). "We recently reported that Gnetin C acts through MTA1/ETS2-mediated mechanisms in prostate cancer and shows significant MTA1-mediated inhibitory effects on cell viability, colony formation, and migration while inducing cell cycle arrest and cell death." (PMID 33255879, 2020). "MTA1 reportedly up-regulated and promoted the progression of tumor growth in many cancers, including lung, liver, breast, ovarian, gastric, and prostate cancers." (PMID 33059651, 2020). "MTA1 is deemed to be a critical upstream regulator of tumorigenesis and targets for c-Myc and Akt, which are key genes in prostate cancer progression." (PMID 32962067, 2020). "Resveratrol, a dietary supplement found in grapes, decreases expression of MTA1 in prostate cancer cells." (PMID 34968229, 2019). "Of note, although the anticancer activity of Gnetin C in prostate cancer cells was mostly MTA1-dependent, we also observed MTA1-independent effects in our molecular and functional studies." (PMID 31487842, 2019). "Other studies have shown that MTA1 expression is correlated with prostate cancer progression, angiogenesis, and metastasis." (PMID 31281798, 2019). "Our results offer the MTA1/CTSB axis as a promising target for novel molecular therapies in prostate cancer bone metastasis." (PMID 30027683, 2018). "We and others have demonstrated the correlation of MTA1 expression with clinicopathological measures of prostate cancer progression: high Gleason score, development of castrate‐resistant disease, recurrence, and bone metastasis." (PMID 30027683, 2018). "Our following studies validated high MTA1 expression in advanced metastatic prostate cancer and bone lesions of patients with prostate cancer." (PMID 30027683, 2018). "We have previously demonstrated the key upstream regulatory role of MTA1 in processes involved in development and progression of prostate cancer." (PMID 30027683, 2018). "Our findings support continued interest in GPE as a chemopreventive and anti-cancer agent against prostate cancer but also emphasize the unique and specific properties of stilbenes on MTA1-mediated anticancer effects on prostate cancer." (PMID 30463302, 2018). "We have also demonstrated the superior MTA1‐targeted anticancer efficacy of pterostilbene/SAHA combination strategy in prostate cancer." (PMID 30027683, 2018). "Here, we report the role of MTA1 in prostate cancer progression and bone metastasis in vitro and in vivo." (PMID 30027683, 2018). "In agreement with our previous reported finding of MTA1 and E‐cadherin (E‐cad) inverse relationship in prostate cancer, shMTA1 cells showed an expected increase in E‐cad levels compared to NS control cells." (PMID 30027683, 2018).
prostate carcinoma (continued). "We found that MTA1 silencing diminished formation of bone metastases and impaired tumor growth in intracardiac and subcutaneous prostate cancer xenografts, respectively." (PMID 30027683, 2018). "To strengthen our findings from smaller sample numbers, we analyzed the publicly available prostate cancer patient dataset from Oncomine database and found significantly higher levels of both MTA1 and CTSB in tumor samples compared to normal prostate tissues." (PMID 30027683, 2018). "In conclusion, our study provides mechanistic and preclinical insight into the critical role of MTA1 in tumor progression and formation of bone metastasis in prostate cancer, at least in part, through the CTSB‐dependent promotion of metastatic pathways." (PMID 30027683, 2018). "We have extensively reported on the critical role of MTA1 and its signaling at all stages of prostate cancer development and progression." (PMID 30027683, 2018). "To explore the clinical significance of the MTA1 and CTSB interrelationship in prostate cancer, we examined the expression of MTA1 and CTSB in a limited cohort of five prostate adenocarcinoma biopsies obtained previously." (PMID 30027683, 2018). "To ascertain the clinical significance of our findings, we investigated the correlation between MTA1 and PTEN in human prostate cancer by analyzing the expression of MTA1 and PTEN mRNA in the GSE41967 dataset from the Gene Expression Omnibus (GEO) database." (PMID 26943043, 2016). "More significantly, it offers pre-clinical proof for pterostilbene as a promising lead natural agent for MTA1-targeted chemopreventive and therapeutic strategy to curb prostate cancer." (PMID 26943043, 2016). "Further, we validated the upregulation of these molecules at protein and mRNA levels in MTA1 knockdown human prostate cancer cells." (PMID 26943043, 2016). "In summary, using clinically relevant disease models of prostate cancer, we demonstrated the MTA1-targeted chemopreventive and therapeutic efficacy of pterostilbene." (PMID 26943043, 2016). "Our studies with prostate cancer cell lines and xenografts have highlighted the functional relevance of MTA1 in promoting tumor growth, invasion, angiogenesis and metastasis." (PMID 26943043, 2016). "Some other investigations have also found higher levels of MTA1 in malignant neoplasms such as prostate cancer, gastric cancer, esophageal and renal cancer than in normal tissues." (PMID 26878004, 2016). "Previously, we have shown that dietary stilbenes, commonly found in grapes and blueberries, inhibit MTA1 expression and function in prostate cancer." (PMID 26943043, 2016). "Results from ChIP-Seq analysis define MTA1 as a key upstream epigenetic driver in prostate cancer initiation and progression." (PMID 26943043, 2016). "The purpose of this study was to determine MTA1- targeted chemopreventive and therapeutic efficacy of pterostilbene, a natural potent analog of resveratrol, in pre-clinical models of prostate cancer." (PMID 26943043, 2016). "This notion has been supported by our previous studies of human specimens, in which MTA1 overexpression was correlated with prostate cancer progression, aggressiveness and metastasis." (PMID 26943043, 2016). "To determine in an unbiased manner if YB-1 or MTA1 mRNA levels are different between normal prostate tissue and prostate cancer, we analyzed 15 human prostate cancer mRNA datasets published between 2001 and 2012, which included 1016 unique patient samples." (PMID 25797255, 2015). "Previous studies on the association between MTA1 and E-cadherin have shown that MTA1 regulates E-cadherin expression through AKT activation in prostate cancer, and that low E-cadherin expression promotes cancer metastasis." (PMID 25609245, 2015).